PHLPP1 (PH domain and leucine rich repeat protein phosphatase 1)
Description:
Protein phosphatase involved in regulation of Akt and PKC signaling. Mediates dephosphorylation in the C-terminal domain hydrophobic motif of members of the AGC Ser/Thr protein kinase family; specifically acts on 'Ser-473' of AKT2 and AKT3, 'Ser-660' of PRKCB and 'Ser-657' of PRKCA. Isoform 2 seems to have a major role in regulating Akt signaling in hippocampal neurons (By similarity). Akt regulates the balance between cell survival and apoptosis through a cascade that primarily alters the function of transcription factors that regulate pro- and antiapoptotic genes. Dephosphorylation of 'Ser-473' of Akt triggers apoptosis and suppression of tumor growth. Dephosphorylation of PRKCA and PRKCB leads to their destabilization and degradation. Dephosphorylates STK4 on 'Thr-387' leading to STK4 activation and apoptosis. Dephosphorylates RPS6KB1 and is involved in regulation of cap-dependent translation. Inhibits cancer cell proliferation and may act as a tumor suppressor. Dephosphorylates RAF1 inhibiting its kinase activity. May act as a negative regulator of K-Ras signaling in membrane rafts (By similarity). Involved in the hippocampus-dependent long-term memory formation (By similarity). Involved in circadian control by regulating the consolidation of circadian periodicity after resetting (By similarity). Involved in development and function of regulatory T-cells (By similarity).
Synonyms: KIAA0606; PHLPP; PLEKHE1; SCOP; PPM3A
Tractability: Small molecule: a high-quality ligand is known. Antibody: UniProt places it where antibodies can reach, with high confidence; its Gene Ontology location is reachable by antibodies, with medium confidence. PROTAC: ubiquitination databases record sites on it; its protein half-life has been measured; a small molecule that binds it is known.
Target class: Plant homeodomain; Epigenetic regulator; Reader
Gene: Protein-coding gene on chromosome 18 (62,715,464 to 62,980,433, forward strand). Ensembl gene ENSG00000081913.
Subcellular location: Cytoplasm; Membrane; Nucleus; Cell membrane (Isoform 2)
Pathways (Reactome):
Signal Transduction: Negative regulation of the PI3K/AKT network
Gene Ontology:
Molecular function: protein binding; protein serine/threonine phosphatase activity
Biological process: negative regulation of phosphatidylinositol 3-kinase/protein kinase B signal transduction; regulation of apoptotic process; regulation of JNK cascade; regulation of MAPK cascade; regulation of p38MAPK cascade; intracellular signal transduction; regulation of T cell anergy
Cellular component: plasma membrane; cytoplasm; cytosol; membrane; nucleus
Genetic constraint (gnomAD): Loss-of-function variants: 35 observed, 84.92 expected, observed/expected ratio (o/e) 0.41, 90% interval 0.31 to 0.55. The upper end of that interval is the gene's LOEUF score, 0.55, which puts it in group 2 of 6, group 1 being the genes least tolerant of losing a copy. Missense variants: 1,823 observed, 1,939.5 expected, observed/expected ratio (o/e) 0.94, 90% interval 0.9 to 0.98. Synonymous variants: 914 observed, 831.91 expected, observed/expected ratio (o/e) 1.1, 90% interval 1.04 to 1.16.
Homologues: Orthologues: chimpanzee PHLPP1 (99% identical), macaque PHLPP1 (98% identical), pig PHLPP1 (88% identical), dog PHLPP1 (87% identical), mouse Phlpp1 (87% identical), rat Phlpp1 (87% identical), rabbit PHLPP1 (82% identical), guinea pig PHLPP1 (67% identical), tropical clawed frog phlpp1 (63% identical), zebrafish phlpp1 (51% identical). Paralogues in human: PHLPP2 (41% identical), SCRIB (13% identical), LRRC7 (12% identical), ERBIN (12% identical), MFHAS1 (10% identical), LRRK1 (9% identical), PIDD1 (8% identical), SHOC2 (8% identical), LRRD1 (8% identical), LRRC1 (8% identical), LRRC40 (8% identical), LRRC8D (8% identical), and 19 more.
Diseases named in the same sentence as PHLPP1 in open-access papers:
PHLPP1 is named in the same sentence as 84 diseases in open-access papers, as found by Europe PMC text mining. Sharing a sentence is not in itself a finding about the gene and the disease. The quoted sentences say what the papers report.
colon carcinoma (20 papers, 2013 to 2025). "Abnormally upregulated in CTX-resistant colon carcinoma cells, miR-199a-5p is also reported to affect cancer cell resistance by targeting PHLPP1." (PMID 31636666, 2019). "Loss of PHLPP expression, either PHLPP1 or PHLPP2, in colorectal cancer was found and overexpression of PHLPP inhibits proliferation of colon cancer both in vitro and in vivo." (PMID 25888950, 2015). "PHLPP1 encodes PH domain and leucine-rich repeat protein phosphatase 1, which dephosphorylates AKT and suppresses the growth of colon cancer and glioblastoma cells." (PMID 24498386, 2014). "Overexpression of PHLPP1 in glioblastoma and colon cancer cells inhibits tumorigenesis in xenografted nude mice, whereas decreased PHLPP1 expression correlates with increased metastatic potential in breast cancer cells." (PMID 24145035, 2013). "In colon cancer, miR-375 have been related to cetuximab resistance through regulation of the AKT pathway by targeting the tumor suppressor gene PHLPP1." (PMID 30388154, 2018). "Similarly, USP46‐mediated PHLPP1 and PHLPP2 stabilization decreases cell proliferation and tumorigenesis in colon cancer cells." (PMID 41000374, 2025). "Similarly, in colon cancer cells hypoxia reduces USP46 mRNA and protein levels and, therefore, diminishes USP46’s stabilizing effect on the tumor suppressors PHLPP1 and PHLPP2, conferring to the colon cancer cells an increased paclitaxel resistance." (PMID 27014628, 2016).
colorectal cancer (20 papers, 2015 to 2025). A primary or metastatic malignant neoplasm that affects the colon or rectum. "One of these mutations was found in PHLPP1, which has been associated with colorectal cancer, and the other was found in USP24, which has been associated with Parkinson’s disease." (PMID 36510265, 2022). "The miR- 761/TRIM29/PHLPP1 axis is activated by circL4R to facilitate the proliferation and spread of colorectal cancer cells." (PMID 36673815, 2023). "In colorectal cancer, one study reported that both PHLPP1 and PhLPP2 dephosphorylated RAF1, thereby inhibiting colorectal cancer proliferation." (PMID 37576883, 2023). "Previous studies have demonstrated that PHLPP1/2 was capable of dephosphorylating RAF in colorectal cancer and increasing tumor invasion and migration by negatively regulating RAS/RAF/MEK/ERK signaling pathways." (PMID 37576883, 2023). "Previous research has shown that USP46 antagonized AKT activity by deubiquitinating PHLPP1 in colorectal cancer." (PMID 37576883, 2023). "HSP47 promotes tumor survival and therapy resistance by modulating AKT signaling via PHLPP1 in colorectal cancer." (PMID 35928554, 2022). "Several research studies have shown that decreased or lost PHLPP1 expression has been detected in many cancers, such as prostate cancer, colorectal cancer, pancreatic cancer and glioblastoma 51-54." (PMID 35711826, 2022). "USP46 had been shown to deubiquitinate the PH domain leucine-rich repeat protein phosphatase 1 (PHLPP1) in colorectal cancer." (PMID 33029497, 2020). "Hsa-miR-375 also seems to affect colorectal cancer cell sensitivity to cetuximab by targeting PHLPP1 and BRAF." (PMID 29930763, 2018). "In colorectal cancer, USP46 has been shown to promote the stabilization of PHLPP1 and subsequent inhibition of the AKT pathway." (PMID 33029497, 2020). "Previously, in colorectal cancer, USP46 had been shown to antagonize the activity of AKT by deubiquitinating PHLPP1." (PMID 33029497, 2020). "The exceptional responders for PHLPP1 and MTCH2 are over-represented by cells from leukemia/lymphoma and colorectal cancer respectively (P = 2.211E-8 and 5.178E-3)." (PMID 27296290, 2016). "By targeting BLM, DENND2D, PHLPP1 or MAOB, miR‐522 could boost tumorigenesis of colorectal cancer, non‐small‐cell lung cancer, glioblastoma and endometrial carcinoma, respectively." (PMID 33369228, 2021). "When PHLPP1 and 2 were knocked out, the expression of epithelial-mesenchymal transition (EMT) markers was increased, which promoted the migration and invasion of colorectal cancer, tumor proliferation and progression and meanwhile negatively regulate MEK signaling pathways." (PMID 37576883, 2023).
prostate carcinoma (20 papers, 2011 to 2025). A carcinoma that arises from epithelial cells of the prostate gland. "We found that the Sag deletion suppressed the progression of prostate cancer induced by Pten-loss with mechanism involving accumulation of Phlpp1 and Deptor to inhibit PI3K/AKT/mTOR signaling pathway." (PMID 27955654, 2016). "PHLPP1 has been described as a tumor suppressor in prostate cancer and there are preliminary findings that aberrant expression of PHLPP1/2 may be associated with poor prognosis in several cancers." (PMID 29562639, 2018). "A number of genetic alterations in genes that encode AKT regulators have been linked to prostate cancer, including kinases (e.g., PDK1), binding proteins (e.g., FKBP5), and phosphatases (e.g., PHLPP1, PHLPP2, and PP2A)." (PMID 32630372, 2020). "Accumulation of Phlpp1 and Deptor with corresponding inactivation of Akt/mTOR was also detected in Sag-null prostate cancer tissues." (PMID 27955654, 2016). "This notion was further supported by our rescued experiment in which simultaneous knockdown of either PHLPP1 or DEPTOR largely abrogated the growth suppression triggered by SAG knockdown in DU145 prostate cancer cells." (PMID 27955654, 2016). "Clusterin was shown to dramatically enhance the migratory and invasive behavior of the normal prostate epithelial cell line PNT1A and the prostate cancer cell line PC3 by regulating the miR-190-5p-PHLPP1 axis, suggesting that miR-190-5p functions as an oncogene in prostate cancer." (PMID 31624470, 2019). "To gain mechanistic insight into SAG action, we used the loss-of-function approach in two human prostate cancer cell lines and found that SiRNA-based SAG knockdown caused in general accumulation of PHLPP1 and DEPTOR with consequential inactivation of pAKT and mTORC1 activity." (PMID 27955654, 2016). "PHLPP1 and PHLPP2 are reported to be lost in 30% and 50% of prostate cancer, respectively, highlighting their clinical importance." (PMID 27955654, 2016). "Consistently, SAG knockdown suppressed the growth and survival of human prostate cancer cells due to accumulation of PHLPP1 and DEPTOR, two new substrates of SAG E3 ligase, which can be partially rescued by simultaneous knockdown of PHLPP1 or DEPTOR." (PMID 27955654, 2016). "Collectively, our results suggested that SAG knockdown triggers accumulation of PHLPP1 and DEPTOR to inactivate the AKT/mTOR axis, leading to observed suppression of growth and survival in prostate cancer cells." (PMID 27955654, 2016). "PHLPP1 and PHLPP2 deep deletion occurs in up to 3.9% and 6.5% of patients with prostate cancer respectively, which could potentially sustain AKT-signaling." (PMID 32630372, 2020).
breast carcinoma (12 papers, 2012 to 2024). "In addition, PHLPP1 is localized on chromosome 16q22.3, a region that encounters frequent loss of heterozygosity in many primary and malignant breast tumors." (PMID 24145035, 2013). "Our results that Xist negatively modulated AKT activation via PHLPP1 regulation suggest a tumor suppressor role of Xist in breast cancer and MDS/MPN." (PMID 27248326, 2016). "Rakha proposed that decreased PHLPP1 expression correlates with increased metastatic potential in breast cancer cells." (PMID 25793736, 2015). "For breast cancer, there is evidence that CCL28 and PHLPP1 may be drivers of breast cancer through the MAPK and AKT pathways, respectively." (PMID 39010058, 2024). "Therefore, TMEPAI positively regulates breast cancer progression by enhancing AKT Ser473 phosphorylation through the degradation of PHLPP1." (PMID 34638419, 2021). "Overexpression of PHLPP1 in a glioblastoma cell line inhibits tumor growth in xenografted nude mice, and decreased expression of PHLPP has been linked to the metastatic potential of 21T breast cancer cells." (PMID 22481935, 2012). "The results of our previous studies showed that BMI1 silencing caused a reduction in AKT phosphorylation and increased the expression of gene coding for PHLPP1 and PHLPP2 phosphatases in endometrial cancer cells HEC-1A and breast cancer MDA-MD-23 cells." (PMID 36497428, 2022). "Knockdown of either Xist or SPEN expression in breast cancer cells suppressed the expression of PHLPP1, a phosphatase in AKT dephosphorylation, and was correlated with increased HDAC3 recruitment to the PHLPP1 promoter." (PMID 27248326, 2016). "Several reports have indicated that PHLPP1 is downregulated in metastatic and aggressive breast cancer cells when compared with the levels in normal cells, but the mechanism of this downregulation of PHLPP1 in these cancer cells is not well studied." (PMID 34638419, 2021). "Interestingly, our TCGA data set analysis showed expression levels of PHLPP1, but not HDAC3, were decreased in breast cancer tissues compared to adjacent normal tissues." (PMID 27248326, 2016).
glioblastoma (12 papers, 2012 to 2025). The most malignant astrocytic tumor (WHO grade IV). "miR‐522 has also been reported to be able to boost colorectal tumorigenesis via targeting BLM, accelerate the progression of endometrial carcinoma by inhibiting MAOB, as well as promote glioblastoma cell proliferation by suppressing PHLPP1." (PMID 33369228, 2021). "Interestingly, a majority of glioblastoma cell lines tested also revealed reduced levels of PHLPP1 mRNA." (PMID 23724143, 2013). "Dysregulation in this negative feedback loop was reported in a subset of high grade glioblastomas, where the level of active AKT determining the expression of its negative regulator PHLPP1 is lost." (PMID 23724143, 2013).
Obesity (8 papers, 2016 to 2025). Accumulation of substantial excess body fat. "To substantiate the efficacy of genetic PHLPP1 inhibition seen in our recent study in a severe in vivo mouse model of hyperglycemia and obesity-associated diabetes progression, we have deleted PHLPP1 in leptin receptor-deficient Leprdb/db (db/db) mice." (PMID 35136063, 2022). "The beneficial effects of PHLPP1 deficiency in a severe mouse model of obesity and diabetes make PHLPP a new target for β-cell-directed diabetes therapy." (PMID 35136063, 2022). "In contrast, the expression of PHLPP1, which hampers the insulin signaling cascade, was reduced in the obesity mice models compared to shSCR-infected mice." (PMID 36866247, 2023). "For example, a clinical study suggested that downregulation of insulin signaling may occur during obesity before T2DM is developed due to hyperactivation of PH domain leucine-rich repeat-containing protein phosphatase (PHLPP-1)." (PMID 34956089, 2021). "Moreover, a positive and strong correlation between PHLPP1 and HSC70 was observed in NW placental tissues, but not in OB populations, again supporting the hypothesis of an impaired CMA function in obesity." (PMID 33920886, 2021).
pancreatic cancer (8 papers, 2013 to 2023). "To determine if PHLPP serves as a tumor suppressor in human pancreatic cancer, we established stable cell lines overexpressing PHLPP1 or PHLPP2 in Panc-1 cells, which express very low levels of endogenous PHLPPs." (PMID 26760962, 2016). "We have interrogated the mRNA expression of PHLPP in several gene expression databases and found that the expression of PHLPP1 is significantly decreased in pancreatic tumor samples compared to normal samples whereas PHLPP2 mRNA expression is less affected." (PMID 26760962, 2016).
diabetes (7 papers, 2013 to 2022). "The elucidation of PHLPP1 involvement will pave the way for further analyses aimed at explaining its role in placental alterations in the context of metabolic disorders and its potential targetability for the treatment of negative consequences of diabetes." (PMID 33920886, 2021). "However, an increase in insulin levels also resulted in the overexpression of PHLPP1 itself, being probably involved in a regulating feedback loop that is lost in diabetes, for reasons that are not yet understood." (PMID 33920886, 2021). "Conversely, the level of PHLPP1, but not PHLPP2, is elevated in diabetes." (PMID 36497428, 2022).
lung cancer (7 papers, 2013 to 2023). A malignant neoplasm involving the lung. "Based on this finding, we constructed a gefitinib resistant lung cancer cell line in vitro experiment, and we found that PHLPP1 expression level decreased." (PMID 37576883, 2023). "Mechanistically, we showed that the antiproliferation activity of USP46 in lung cancer is mediated through the inhibition of AKT activity via deubiquitination of PHLPP1." (PMID 33029497, 2020). "USP46 is downregulated in lung cancer and suppresses the proliferation of lung cancer cells by inhibiting the PHLPP1/AKT pathway." (PMID 33029497, 2020). "Compared to the control cells, the overexpression of USP46 led to a decrease in ubiquitination in PHLPP1, indicating that USP46 deubiquitinates PHLPP1 in lung cancer cell lines." (PMID 33029497, 2020). "USP46 was further shown to inhibit lung cancer cell proliferation under conditions of normal growth and during radiation-induced DNA damage by antagonizing the ubiquitination of PHLPP1 resulting in the inhibition of AKT signaling." (PMID 33029497, 2020). "Herein, we investigated the potential role of USP46 in lung cancer tumorigenesis and found that the expressions of USP46 and PHLPP1 were downregulated in lung cancer." (PMID 33029497, 2020). "Quantitative real-time polymerase chain reaction (qRT-PCR) and western blotting (WB) were used to measure the expression levels of USP46 and PHLPP1 in lung cancer tissue and adjacent normal tissue from patients with lung cancer." (PMID 33029497, 2020). "In this study, we identified a strong downregulation of the expressions of USP46 and PHLPP1 in lung cancer tissues relative to normal adjacent tissues." (PMID 33029497, 2020). "On this basis, the expression of both USP46 and PHLPP1 were found in low level in lung cancer." (PMID 37576883, 2023). "However, the detailed relationship between USP46 and the PHLPP1/AKT pathway is still less investigated in lung cancer." (PMID 33029497, 2020). "Clinically, we showed that USP46 and PHLPP1 are downregulated in patients with lung cancer." (PMID 33029497, 2020). "USP46 is a deubiquitinase, so we hypothesized that USP46 deubiquitinates PHLPP1 in lung cancer cells." (PMID 33029497, 2020). "Whether PHLPP2 is regulated in a similar manner as PHLPP1 with dysregulations in its expression in lung cancer can be examined in the future." (PMID 23724143, 2013). "Mechanismly, those effect might be due to the PHLPP1 expression was negatively correlated with p-AKT or p-ERK, which was involved in tumor progression and were associated with aggressiveness in advanced lung cancer." (PMID 37576883, 2023). "Therefore, present results suggested that USP46 might be positively correlated with PHLPP1 in lung cancer tissues." (PMID 33029497, 2020). "At the same time, we elucidated related proteins that directly act on PHLPPs in lung cancer, including USP46 through the effect of PHLPP1 on AKT, and the effect of miR-205 on PHLPP2 and miR-190 on PHLPP1." (PMID 37576883, 2023).
gastric cancer (6 papers, 2015 to 2022). A primary or metastatic malignant neoplasm involving the stomach. "Thus, it appears that MLN4924/PHLPP1-induced autophagy was protective for gastric cancer cell growth, and the blockage of autophagy enhanced the efficacy of MLN4924." (PMID 27063292, 2016).
hepatocellular carcinoma (6 papers, 2016 to 2025). A malignant tumor that arises from hepatocytes. "PHLPP1/2 expression is frequently decreased in human cancers such as colon, breast, ovarian, prostate and hepatocellular carcinoma (HCC)." (PMID 28082369, 2017). "However, there were still conflicting reports that miR-3127 actually acted as an oncogene in hepatocellular carcinoma by activating AKT/FOXO1 signaling, via directly targeting the 3′-UTR of PHLPP1/2." (PMID 32194636, 2020).